GSK3B (glycogen synthase kinase 3 beta)
Diseases named in the same sentence as GSK3B in open-access papers (continued):
Sharing a sentence is not in itself a finding about the gene and the disease.
lung carcinoma (continued). "In terms of enhancing the antitumor activity of adriamycin, nobiletin inhibits Akt and Wnt/β-catenin signaling pathway by increasing GSK-3β activity, and leads to decreased lung cancer cells viability." (PMID 36874011, 2023). "A study revealed that FBLN3 restrained the stemness of lung cancer cells via the IGF1R/PI3K/AKT/GSK3β signaling pathway." (PMID 36385964, 2022). "GSK-3β/β-catenin is considered to be an important downstream cascade of AKT in regulating cancer metastasis; thus, we investigated if ZSD inhibited growth and metastasis in lung cancer by modulating AKT/GSK-3β/β-catenin signaling." (PMID 33777320, 2021). "These phenomena confirmed the critical role of the AKT/GSK-3β/β-catenin pathway in ZSD against lung cancer." (PMID 33777320, 2021). "Our results elucidated a novel mechanism whereby ZVI-NP disrupts redox balance and induces ferroptosis of lung cancer cells by triggering AMPK/mTOR signaling to promote GSK3β/β-TrCP degradation of NRF2." (PMID 34093872, 2021). "It has been reported that activation of the GSK-3β/β-catenin pathway promotes the cell proliferation and leads to development of lung cancer." (PMID 33777320, 2021). "Remarkably, IL-17RB providing signal across ERK/GSK-3β/β-catenin route is connected to lung cancer's EMT." (PMID 34336101, 2021). "Recently, the suppression of CSC phenotype in lung cancer induced by alpha-lipoic acid was posited to be driven by the reduction of p-Akt level, which led to the depletion of p-GSK3β, β-catenin, and Oct4." (PMID 34349823, 2021). "Since the stemness factors are known to be transcriptionally activated by Akt/GSK-3β/β-catenin signal, the modulation on stemness transcription factors was further confirmed in CSCs obtained from lung cancer H23 and A549 cells via RT-qPCR." (PMID 34063628, 2021). "The obtained results strongly support the role of jorunnamycin A in modulating CSC phenotypes in human lung cancer cells via the GSK-3β/β-catenin pathway." (PMID 34063628, 2021). "We also found that the AKT/GSK-3β/β-catenin pathway medicated anticancer effect of ZSD in lung cancer cells." (PMID 33777320, 2021). "Based on a network pharmacology-based analysis and experimental evidence, we demonstrated that the AKT/GSK3β/β-catenin signaling pathways were responsible for BHGJT-induced apoptosis in lung cancer cells." (PMID 34659548, 2021). "Stimulation of the ERK/GSK-3β/β-catenin path after IL-17RB encouragement did promote the intrusion and relocation of human lung cancer cell lines—H441 and CL1-0, in in vitro studies." (PMID 34336101, 2021). "Taken together, our experimental results showed for the first time that ZSD exerted specific anticancer activity in lung cancer cells partially through inhibition of the AKT/GSK-3β/β-catenin signaling pathway in vitro and in vivo." (PMID 33777320, 2021). "We detected the expression of AKT, p-AKT and its crucial downstream GSK3β in lung cancer cells upon treatment with BHGJT." (PMID 34659548, 2021). "It was also reported that β-catenin levels vary in different lung cancer cell lines undergoing knockdown of GSK3β." (PMID 32503133, 2020). "Aberrant activation of PI3K/AKT/GSK3β axis is one of the critical initial biological events in deregulating cell cycle rhythm in lung cancer cells." (PMID 33027592, 2020). "Treatment of lung cancer CSCs with sulforaphane resulted in induction of miR-19 and suppression of GSK-3β and increased WNT/β-catenin expression." (PMID 32365809, 2020). "Recently, it was shown that, by reducing the expression of protein phosphatase 2A (PP2A), COX-2/PGE2 can induce the expression of migration inducing gene-7 (MIG-7) to activate the PI3K/Akt/GSK-3β pathway and subsequently promote lung cancer metastasis." (PMID 32678165, 2020).
lung carcinoma (continued). "The mechanism underlying the specificity in the aaptamine-induced anticancer function is the regulation of cell cycle and its upstream PI3K/AKT/GSK3β signal axis in which aaptamine is sensitive to dephosphorylate AKT and GSK3β in lung cancer cells." (PMID 33027592, 2020). "Cordycepin can bind to the AR3 to inhibit cell proliferation by inactivating glycogen synthase kinase (GSK)-3β/β-catenin signaling pathway, and subsequently suppressing cyclin D1 and c-myc expression in melanoma and lung carcinoma cells." (PMID 33172093, 2020). "We have previously shown in lung cancer cells that GSK3α and to a lesser extent GSK3β are inhibited by the advanced clinical candidate tivantinib (ARQ197), which was designed as a MET inhibitor." (PMID 30679640, 2019). "Using the MCTS xenograft mouse model, we demonstrated that inhibition of GSK-3β reduces lung cancer volume, and in combination with Gefitinib, has a synergistic effect on lung cancer therapy." (PMID 30709379, 2019). "The authors observed that SC-treated lung cancer cells exhibit an increased phosphorylation of Akt and GSK-3β." (PMID 31921388, 2019). "Synergization with cisplatin, pristimerin led to apoptosis via inhibiting the miR-23a, regulating PTEN/Akt signaling-related PTEN and the phosphorylation of Akt and GSK3β in lung carcinoma NCI-H446 and A549 cells." (PMID 31354475, 2019). "The Y216-phosphorylated active form of GSK3B is significantly decreased in squamous cell carcinoma and in lung cancer, inhibiting GSK3B increases the expression of the transcriptional repressor Snail, which suppresses E-cadherin and promotes EMT." (PMID 31108958, 2019). "Taken together, these results demonstrated that cypripedin suppresses the mesenchymal transition in lung cancer via inhibition of Akt, which in turn activates GSK-3β and leads to Slug degradation." (PMID 29789636, 2018). "It has been shown that GSK-3β inhibition potentiates c-FLIPL degradation in human lung cancer cells." (PMID 29445085, 2018). "Collectively, TM4SF4-derived signaling pathways including GSK3β/β-catenin and JAK2(or FAK)/STAT3 appear to be focused on the secretion level of OPN and thus strengthen EMT-associated CSC-like properties in lung cancer cells." (PMID 29254164, 2017). "In order to provide the clinical evidence of the regulation of GSK3β Ser9 phosphorylation by hnRNPK in lung cancer, we have performed the immunohistochemical essays using two commercialized tissue microarrays." (PMID 26972480, 2016). "Although the overexpression of GSK-3β and its function as a tumor promoter in lung cancer has been demonstrated, the role of GSK-3α in lung cancer remains elusive." (PMID 27049759, 2016). "We conclude that OLA1 contributes to the EMT of lung cancer cells through regulating the GSK3β/Snail/E-cadherin signaling pathway." (PMID 26863455, 2016). "Our previous study demonstrates that rDP2 inhibits GSK3β through Akt-mediated phosphorylation at serine 9 in human lung carcinoma A549 cell." (PMID 26697166, 2015). "Downregulation of ILK expression and CDDP treatment, in combination, is a more effective approach for the treatment of lung cancer through affecting downstream gene expression, including p-GSK3β, p-AKT, AP-1, β-catenin, cyclin D1 and MMP-9." (PMID 25760437, 2015). "In this study, we first discovered that PARVA can activate the GSK3β—AP-1–MMP9 pathway in lung cancer cells." (PMID 25738875, 2015). "First, we performed co-immunoprecipitation assay and observed that endogenous Gsk-3β interacts with h-Prune-Flag in A549 lung cancer cell line." (PMID 25026278, 2014). "Altogether these data indicate that β-catenin nuclear translocation followed by LiCl-induced canonical WNT signaling activation in lung cancer cells requires the h-Prune inhibitory effects on Gsk-3β activity." (PMID 25026278, 2014).
lung carcinoma (continued). "Though a positive role for GSK-3β involvement in PDCD4 protein regulation has been recently reported in lung cancer cells, our studies provide the first evidence for transcriptional regulation of PDCD4 by GSK-3β in a developmental neuronal setting." (PMID 24837604, 2014). "In this study, it was demonstrated that the inhibition of GSK3β greatly suppressed the invasiveness of NSCLC cells, regardless of the cancer type, and this result supports the prognostic value and tumor promoter role of GSK3β in lung cancer." (PMID 24618715, 2014). "In these 4 cell lines, except in H292 pGS, was detected, which suggested high activity of GSK3β in human lung cancer." (PMID 24618715, 2014). "One interesting finding from our current study was that side-stream smoke exposure led to activation of Akt and GSK3β in myocardium, consistent with the findings of activation of Akt and GSK3β in epithelial cell systems prompting development of lung cancer." (PMID 23431404, 2013). "It has been reported that the progressive inactivation of GSK3β, which is related to the increase in phosphorylation of GSK3β, is critical for the progression of lung cancer." (PMID 22343623, 2012). "In conclusion, this study revealed synthetic lethality between FHIT and GSK3β in lung cancer cells." (PMID 39762409, 2025). "We next examined whether GSK3β was involved in the activation of the DSB repair pathway in lung cancer cells." (PMID 39762409, 2025). "Moreover, collagen XVII promotes epithelial-to-mesenchymal transition and increased metastatic spread in lung cancer through regulation of the FAK/AKT/GSK3β pathway." (PMID 40728119, 2025). "Recent studies suggested that blockade of GSK-3β could suppress the viability of neuroblastomas, prostate cancer, and lung cancer." (PMID 38555280, 2024). "Taken together, our study delineated a previously unknown mechanism of a positive feedback loop between IGF2BP2 and SLC7A5, and highlighted the role of the FBW7/GSK3β/IGF2BP2/SLC7A5 axis in radioresistance in lung cancer." (PMID 38281999, 2024). "Similarly, sulforaphane treatment inhibited GSK3β and the stem-like properties of lung cancer cells in vitro, by reducing the expression of miR-19." (PMID 38972997, 2024). "In lung cancer progression, α-parvin acts as an oncogene by activating Akt and inhibiting GSK3β." (PMID 39329755, 2024). "Recent studies illustrated that SFN could suppress the EMT in lung cancer cells by inhibiting the GSK3β/β-catenin pathway and ERK5 activation." (PMID 36899823, 2023). "In addition, we demonstrate that HORMAD1 activates the Wnt/β-catenin pathway to induce EMT during lung cancer metastasis by regulating AKT/GSK-3β signaling." (PMID 35347116, 2022). "FAM83A can inhibit GSK3β activity and increase the level of active unphosphorylated β-catenin; active β-catenin then transports into the nucleus and activates the Wnt signaling pathway in lung cancer cells." (PMID 36612054, 2022). "MiR-1246 could promote metastasis and invasion in lung cancer cells by targeting glycogen synthase kinase-3β (GSK-3β)-mediated Wnt/β-catenin pathway." (PMID 36251659, 2022). "The suppression of Akt and p-GSK-3β has been remarkably noted to suppress CSCs in lung cancer." (PMID 34063628, 2021). "Thus, the inhibition on Akt/GSK3β pathway efficiently decreases CD133high-expressing cells and tumor-initiating activity in lung cancer." (PMID 34349823, 2021). "Serine threonine tyrosine kinase 1 (STYK1, also known as NOK), a member of the receptor tyrosine kinases (RTKs) family, can promote metastasis of lung cancer through inducing epithelial-mesenchymal transition (EMT) by activating the AKT/glycogen synthase kinase 3 beta (GSK3B) pathway." (PMID 34742351, 2021). "Previous research also proposed that FAM83A can inhibit GSK3β activity and increase the level of active unphosphorylated β-catenin and active β-catenin can transports into the nucleus thus activating the Wnt signaling pathway in lung cancer." (PMID 34641907, 2021).
lung carcinoma (continued). "This indicates that GSK3β may function independently of the β-catenin pathway in lung cancer, consistent with previous reports on colorectal, stomach, pancreatic and liver cancers." (PMID 32503133, 2020). "Moreover, OLA1 contributes to EMT in lung cancer by modulating the GSK3β/Snail/E-cadherin signaling." (PMID 32528278, 2020). "For example, Zhou at al. demonstrated that SCs conditioned by lung cancer cell secreted CXCL5 to activate PI3K/Akt/GSK-3β signaling and induced the expression of EMT regulators Snail and Twist in tumor cells, thereby aiding the spread and metastasis of lung cancer cells." (PMID 32308766, 2020). "Tivantinib was shown to inhibit GSK3α and to a lesser extent GSK3β in lung cancer cells." (PMID 32887519, 2020). "We then checked the interaction between endogenous SMAD4 and GSK-3β in A549 lung cancer cells." (PMID 33199824, 2020). "DEPTOR inhibits the EMT process by inhibiting the AKT/GSK3β/snail pathway in lung carcinoma cells." (PMID 31228948, 2019). "Our results provide clear evidence that reciprocal crosstalk between NSCLC cells and HUVECs leads to the endothelial-to-mesenchymal transition via the activation of GSK-3β in multicellular tumor spheroid models, and thereby plays a central role in resistance to lung cancer therapy." (PMID 30709379, 2019). "Hence, further experiments to demonstrate specific activation of GSK-3β in HUVEC induced by co-culture with lung cancer cells in MCTSs should be performed." (PMID 30709379, 2019). "However, Gln-supplemented animals exhibited an increase in phosphorylated GSK3b, suggesting an inactivation of GSK3b that has been recently shown to favor glutaminolysis and thus glutamine utilization as a carbon source in lung cancer cells." (PMID 31208031, 2019). "In NCI-H446 and A549 lung carcinoma cells, combination with cisplatin could induce cell apoptosis through inhibiting the miRNA-23a and Akt/GSK3β signaling pathway." (PMID 31354475, 2019). "In summary, these findings suggest that targeting EndMT through GSK-3β inhibition in HUVECs might represent a promising therapeutic strategy for lung cancer therapy." (PMID 30709379, 2019). "Expression of the major component in the Wnt pathway (glycogen synthase kinase-3β [GSK3β]) and downstream effectors of the Wnt pathway (β-catenin, Cyclin D1, c-Myc, and Survivin) was assessed by western blot in lung cancer cells in which HOXA4 had been overexpressed or knocked down." (PMID 29700285, 2018). "Previous data implicated that GSK-3β, inactivated by the activation of MAPK and AKT signaling pathway, could promote the degradation of Slug, and subsequently triggers EMT in lung cancer cells." (PMID 29921293, 2018). "Collectively, these data suggest that HOXA4 is a potential diagnostic and prognostic marker in lung cancer, and its overexpression could inhibit lung cancer progression in part by promoting GSK3β transcription." (PMID 29700285, 2018). "MiR-554a maintained self-renewal of lung cancer stem cells via downregulating Gsk3β." (PMID 28076327, 2017). "To address this hypothesis, we performed an in silico analysis to identify regulatory genes whose expression correlation to GSK3β messenger RNA utilizing two lung cancer cell line array datasets." (PMID 28196122, 2017). "Strikingly, in the same histological section of lung cancer, we were able to simultaneously observe the low hnRNPK expression accompanied with the high level of phospho-GSK3β in a region (the arrows), and the opposite pattern in a neighbouring zone (the stars)." (PMID 26972480, 2016). "There is evidence that GSK-3β is overexpressed in lung cancer." (PMID 27049759, 2016). "Furthermore, EFEMP1 suppresses both the epithelial-to-mesenchymal transition and self-renewal of lung cancer stem cells by modulating the IGF1R/PI3K/AKT/GSK3β pathway." (PMID 25987128, 2015).
lung carcinoma (continued). "Recently, a number of studies have shown that GSK3β can positively regulate the proliferation and apoptosis of tumor cells, although the precise role of GSK3β in lung cancer remains unknown." (PMID 24618715, 2014). "Therefore, the results of previous studies and our current study suggest that GSK3β has anti-apoptotic effects in NSCLC, which cause it to function as a tumor promoter in lung cancer." (PMID 24618715, 2014). "Although little attention has been paid to the expression of GSK3β in lung cancer, evidence suggests that the overexpression of p-GSK3β may serve as a marker for worse prognosis in lung cancer." (PMID 24618715, 2014). "For this reason, we asked whether the h-Prune/Gsk-3β interaction can also be identified in lung cancer cell lines, and if this interaction has a role in canonical WNT signaling." (PMID 25026278, 2014). "While our results indicate that nestin acts through the Akt-GSK3β-Rb signaling pathway to contribute to proliferation in lung cancer cells, other aspects of tumor malignancy, such as angiogenesis, lymphangiogenesis and tumor metabolism, are yet to be directly examined." (PMID 24498263, 2014). "Downregulation of nestin efficiently inhibited lung cancer cell proliferation, which might be through affecting cell cycle arrest and Akt-GSK3β-Rb signaling pathway." (PMID 24498263, 2014). "Moreover, previous studies have shown GSK3β is downregulated when lung carcinoma cells are exposed to cigarette smoke extract." (PMID 23166798, 2012). "Since dysregulation of Wnt/β-catenin signaling pathway that leads to uncontrolled tumor cell proliferation, metastasis, and resistance to apoptosis has been reported in lung cancer, Wnt and its downstream targets, GSK-3β, β-catenin, and MMPs, were included to study the effects of MCME on CL1 cells." (PMID 23320038, 2012). "Hence, we surmised that the FBW7/GSK3β/IGF2BP2/SLC7A5 axis may modulate lung cancer radiosensitivity." (PMID 38281999, 2024). "Moreover, Pellino-1 increased the phosphorylation (inactive form) of GSK3β in lung cancer cells." (PMID 28009353, 2017). "Furthermore, negative correlation between the level of hnRNPK and the Ser9 phosphorylated GSK3β could be established in both lung cancer and normal tissues." (PMID 26972480, 2016). "Moreover, this miRNA was also found able to reduce the GSK3β expression, always in lung cancer stem cells, as well as of activating the Wnt signaling pathway in gastric cancer cells through the induction of epithelial-mesenchymal transition (EMT) and the expression of VIM, SNAI1 and ZEB1." (PMID 27275761, 2016). "The current knowledge with regard to GSK3β in lung cancer progression is based on the clinical observation that phosphorylated GSK3β (Ser 9, kinase dead) might be a good prognostic marker for the epidermal growth factor receptor (EGFR) overexpressing lung carcinoma." (PMID 24312384, 2013). "To explore the underlying mechanism of the observed synthetic lethality induced by GSK3β inhibition, we first compared the basal expression levels of GSK3β in FHIT-expressing and FHIT-mutant lung cancer cell lines." (PMID 39762409, 2025). "In lung cancer, MTHFD2 is activated by ATF4 to maintain redox homeostasis and contributes to cancer progression by regulating AKT/GSK-3β/β-catenin signaling." (PMID 40918462, 2025). "In lung cancer cells, Zi Shen decoction (ZSD), a traditional Chinese medicine, exhibited anticancer effects by regulating the AKT/GSK3-β/β-catenin pathway." (PMID 41217667, 2025). "Specifically, the FBW7/GSK3β/IGF2BP2/SLC7A5 axis was characterized and shown to play a vital role in lung cancer radiosensitivity." (PMID 38281999, 2024). "The activated adenosine receptors induce the expression of Snail through the Akt‐Gsk3β pathway, promoting the progression of EMT in lung cancer cells." (PMID 38545257, 2024).